ARID2 (AT-rich interaction domain 2)
Diseases named in the same sentence as ARID2 in open-access papers (continued):
Sharing a sentence is not in itself a finding about the gene and the disease.
tumor (continued). "Leveraging advanced bioinformatics techniques, the identification of 12 crucial genes (ETNK1, BICRA, IL-1R1, KDM3A, ARID2, GSK3β, EZH2, NOTCH1, SMARCA4, FOS, CREB1, CASP3) associated with the tumor-suppressing miR-101-3p network stands out as a notable achievement." (PMID 40074445, 2025). "In recent investigations, ARID2 expression was reported to be considerably decreased in metastatic HCC tissues, and it was linked with poor prognosis in HCC patients and significantly correlated with tumour metastasis." (PMID 39471843, 2024). "These in vitro experimental results consistently point to ARID2’s tumor-suppressive function." (PMID 39727945, 2024). "The up-regulation of ERBB3 in ARID2-deficient cells indicates that the absence of ARID2 promotes tumor progression through a critical pathway, underscoring its importance in maintaining cellular homeostasis and preventing tumorigenesis." (PMID 39727945, 2024). "First, we confirmed the tumor-suppressive role of ARID2 in TFE3-RCC." (PMID 39727945, 2024). "Several studies have confirmed the tumor suppressive properties of ARID2." (PMID 39054516, 2024). "Whole exome sequencing (WES) identified a KEAP1/STK11 co-mutation with loss of function for both genes, a MAP2K1 activation, and an ARID2 loss of function, as well as a low tumor mutational burden (TMB) with no actionable mutation (4.4 mut/Mb)." (PMID 39170614, 2024). "In vivo experiments further validated that ARID2 KO promoted tumor growth." (PMID 39727945, 2024). "Furthermore, the ARID2 mutation cohort showed trends of increased T-cell CD8+ and myeloid dendritic cell presence within the tumor microenvironment (TME) compared to ARID-WT." (PMID 38341515, 2024). "In conclusion, these multifaceted and mutually corroborating experimental results strongly support our hypothesis: ARID2 likely plays a key tumor-suppressive role in TFE3-RCC." (PMID 39727945, 2024). "Lastly, the loss of Arid2 promoted the expression of KLRD1 and inhibited TCF1 and TOX expression in the CXCR6+CD44+ cluster, further indicating an increased effector profile of tumor-specific CD8+ T cells following PBAF deletion." (PMID 37330910, 2023). "Notably, Arid2-deleted CD8+ T cells exhibited a significant increase in the number and frequency of tumor-specific Arid2-deficient CD8+ T cells compared with their wild-type counterparts." (PMID 37330910, 2023). "In addition, related studies have reported that ARID2, SMARCC1, SMARCD1‐3 and other subunits have a low mutation probability in tumours, which is manifested as delection." (PMID 36883311, 2023). "Several studies have indicated the tumor-suppressive function of ARID2 in tumor pathogenesis." (PMID 36567903, 2022). "Furthermore, tumor suppressor genes with a mutational frequency of >10% in cell lines involved SMAD4, SMARCA4, ARID1A, ARID2, and RBM10." (PMID 36013219, 2022). "Another study demonstrated that ARID2 is involved in cancer cellular immunotherapy resistance, which suggested that ARID2 might also regulate T cell cytotoxicity in the tumor microenvironment." (PMID 36567903, 2022). "Mutations in ARID1A, ARID2, BRAF, SMARCA4, TERT and IDH1 were significantly exclusive to intracranial metastases while the same variants remained undetected in the corresponding extracranial tumor tissues." (PMID 33578810, 2021). "All the researches showed consistently ARID2 the function of a tumor suppressor." (PMID 33592583, 2021). "Mutations in ARID1A (p = 0.0205), ARID2 (p = 0.0207), BRAF (p = 0.023) SMARCA4 (p = 0.015), TERT (p = 0.0041), and IDH1 (p = 0.0041) were significantly exclusive to BM while the same variants remained undetected in the corresponding extracranial tumor tissues." (PMID 33578810, 2021). "ARID2 has been recently thought of as modulating the tumor immune landscape in HCC." (PMID 32977645, 2020). "Several studies suggested or reported ARID2 tumor suppressor properties." (PMID 32977645, 2020).
tumor (continued). "In addition, miR-376c-3p expression was found to be significantly higher in HCC samples compared to non-tumor-adjacent tissues while ARID2 was inversely downregulated in HCC samples." (PMID 32977645, 2020). "Regarding tumor initiation, one in vitro study describes a role for ARID2 in recruiting XPG (xeroderma pigmentosum complementation group G), a component of the nucleotide excision repair (NER), upon UV irradiation or exposure to carcinogenic chemical compounds like benzo{a}pyrene and FeCl3." (PMID 32977645, 2020). "Our mutational analysis shows that ARID2 is a highly mutated SWI/SNF subunit surpassing the mutation frequency of ARID1A, which is the subunit that is the main mutated SWI/SNF subunit in other tumor types." (PMID 33321963, 2020). "The xenograft model evidenced similar tumor-retarding effects of ARID2." (PMID 27351279, 2016). "Recently, ARID2 has been identified as a novel tumor suppressor gene." (PMID 27351279, 2016). "It has been reported that the mutation of AT-rich interaction domain 2 (ARID2), which is a constituent of the SW1/SNF complex, might be a tumor mutation burden in HCC and may correlate with the efficacy of ICIs; however, it has not yet reached the stage of clinical application." (PMID 34071550, 2021). "The data suggest that the inhibition of ARID2 in ARID2-non-mutated tumours could enhance their ICI response, but this still needs to be evaluated." (PMID 34445385, 2021). "Moreover, ARID2 knockdown significantly promoted KL tumor growth." (PMID 34858604, 2021). "However, knockdown of ARID2 significantly promoted tumor formation in orthotopic tumor models." (PMID 27351279, 2016). "To harness this new knowledge, we performed ACT experiments with Arid2-deleted CD8+ T cells and found increased tumor control mediated by heightened effector cell proliferation and limited exhaustion." (PMID 37330910, 2023). "Results from the TIMER database showed that the expression of ARID1A, ARID2, and ARID4A was positively related to tumor purity (p < 0.05), indicating that these three genes were lowly expressed in the HCC immune microenvironment." (PMID 36034939, 2022). "The expressions of ARID1A, ARID2, ARID3C, JARID1C and JARID2 were strongly correlated with tumour stage." (PMID 35127746, 2021). "We further established a KLA tumor-derived primary cell line (hereafter refered to as KLA cells) and found that ectopic expression of ARID2 significantly inhibited the migratory capability of KLA cells." (PMID 34858604, 2021). "The expression of ARID1A and ARID2 inhibited the proliferation and migration of LIHC cells and, thus, act as tumour suppressors." (PMID 35127746, 2021). "Loss of SWI/SNF function has been associated with malignant transformation, and recent data demonstrate that several components of the SWI/SNF complexes, including ARID1A, ARID2, SMARCA4 (BRG1), SMARCB1 (SNF5), and PBRM1, function as tumor suppressors." (PMID 27351279, 2016). "Meanwhile, E2F1 silencing inhibited tumor cell growth and invasiveness, accompanied by markedly decreased binding of E2F1 at CCND1 and CCNE1 gene promoters in ARID2-depleted cells." (PMID 27351279, 2016). "ARID2 knockout (KO) enhanced TFE3-RCC cell migration, proliferation, and tumor growth." (PMID 39727945, 2024).
tumor (continued). "To investigate the tumor-specific CD8+ T cell response, we isolated CD8+ T cells on day 8 after ACT and observed a significant increase in the frequency and cell number of Arid2-deficient CD8+ P14 cells in the tumor and draining lymph nodes." (PMID 37330910, 2023). "Several subunits of the SWI/SNF complex including SNF5 (SMARCB1/INI1/BAF47), ARID1A (BAF240A), SMARCA4 (BRG1), ARID1B (BAF250B), ARID2 (BAF200) and PBRM1 (BAF180) exert critical tumor suppression activities, through inhibiting oncogenic transcription, cell cycle, epigenetic instability and etc.." (PMID 33670012, 2021). "Interestingly, multiple miRNAs (miR) were found to decrease ARID2 levels in HCC, thereby promoting tumor growth and invasion." (PMID 32977645, 2020). "As ARID2 repression is closely correlated with cell proliferation and invasiveness, the expression of cell growth and aggressiveness markers Ki-67, E2F1, cyclin D1, and cyclin E1 were then evaluated in tumor tissues." (PMID 27351279, 2016). "Finally, to compare the wild-type and Arid2-deleted CD8+ T cell response independent of the tumor volume, we cotransferred an equal number of congenic sgCtrl and sgArid2 P14 CD8+ T cells into B16-GP33-bearing recipient mice." (PMID 37330910, 2023). "The present study demonstrates that physical interactions between ARID2 and the transcriptional factor E2F1 play pivotal roles in ARID2-mediated suppression of cyclin D1 and cyclin E1, supporting the notion that ARID2 acts as a tumor suppressor by targeting the Rb-E2F signaling pathway." (PMID 27351279, 2016). "Similarly, ARID1B, ARID2, JARID1C could function mainly as tumor suppressors in cancers." (PMID 33592583, 2021). "However, if USP2 could affect tumor progression through targeting ARID2 has not been reported." (PMID 36567903, 2022). "While SWI/SNF complexes and ARID2 have been involved in both DDR and gene regulation, it is still not clear to what extent their tumor suppressive effect is due to impaired DDR or aberrant transcriptional regulation." (PMID 32977645, 2020). "Therefore, the findings suggested that the absence of Arid2 results in the generation of highly proliferative and less exhausted intra‐tumoral effector CD8+ T cells, ultimately leading to enhanced tumour control." (PMID 39169517, 2024).
cancer (83 papers, 2014 to 2025). A tumor composed of atypical neoplastic, often pleomorphic cells that invade other tissues. "In the protein network analysis, we found a network (SCAF11-ARID2-RASA2-ZBTB38) centered in RASA2, together with the chromatin remodeling factor ARID2, also mutated in various cancer types." (PMID 38892353, 2024). "Another component of the PBAF complex, ARID2, is also frequently mutated in various types of cancers." (PMID 39727945, 2024). "Loss-of-function mutations in the ARID2 protein are also common in many types of cancer, including HCC." (PMID 39471843, 2024). "The implication of ARID2 mutations and, more broadly, the disruption of chromatin regulatory mechanisms in cancer suggests the necessity of anticancer therapies targeting chromatin-associated proteins." (PMID 39471843, 2024). "Cancers with inactivating ARID2 mutations are more sensitive to PD-1 blockade, as well as to other types of immunotherapies." (PMID 36901733, 2023). "Loss of ARID2 function due to these genetic changes can lead to dysregulation of gene expression, contributing to cancer development and progression." (PMID 38023196, 2023). "Mutations of the ARID2 gene, which is involved in chromatin remodeling gene, are found in many human cancers." (PMID 35174643, 2022). "ARID2 partial or complete loss of physiological function is present in many cancers and is thought to play vital roles in carcinogenesis and cancer progression." (PMID 36178086, 2022). "Generally, mutated ARID1A, ARID1B and ARID2 were all related to the good prognosis of ICI therapy based on the pan-cancer population." (PMID 35239432, 2022). "Consistent with a role in cancer progression, ARID2 loss was found to suppress metastasis in a mouse model of hepatocellular carcinoma." (PMID 35323214, 2022). "Available PBAF complex mutations included PBRM1 and ARID2, present at 7.4% and 6.5%, respectively, across the pan-cancer cohort; LOF frequencies are 3.9% and 2.3%, respectively." (PMID 32820162, 2020). "The involvement of ARID2 mutations, and more widely the disruption of chromatin regulatory processes in cancer, point towards the need for anti-cancer therapies targeted on chromatin-associated proteins." (PMID 32977645, 2020). "In this regard, ARID2 mutations are associated with increased cytolytic activity in multiple types of cancers." (PMID 29728604, 2018). "According to data, the interruption of the DNA repair machinery, nucleotide excision repair (NER), due to ARID2 deletion could induce DNA damage, increasing the risk of developing cancer and hypermutations." (PMID 39471843, 2024). "Cancer patients harboring mutated ARID1A, ARID1B or ARID2 benefit more from cancer immunotherapy." (PMID 35239432, 2022). "HCC is an example of cancer that frequently harbors ARID2 mutations." (PMID 32977645, 2020). "A recent study also suggested that ICIs may be used as favourable candidates for treating ARID2‐mutated cancers displaying the hypermutator phenotype, including HCC." (PMID 32162380, 2020). "Finally, Arid2, together with Pbrm1, is linked to cancer cell immunotherapy resistance." (PMID 32977645, 2020). "By using large‐scale public data sets, we validated that ARID2 knock‐out could lead to similar molecular changes in vivo and, moreover, observed a higher number of somatic mutations in ARID2‐mutated subtypes than in the ARID2 wild‐type across various types of cancers including HCC." (PMID 29863171, 2018). "Recent studies have reported that ARID2 plays a crucial role in balancing the effector and exhaustion states of mature T cells in chronic viral infections and cancer." (PMID 40342423, 2025). "Surveying 829 polyclonal gastric microbiopsies by targeted sequencing, we find somatic 'driver' mutations in a distinctive repertoire of known cancer genes, including ARID1A, ARID1B, ARID2, CTNNB1 and KDM6A." (PMID 40108450, 2025).
cancer (continued). "For instance, PBRM1, ARID2, and BRD7, which encode subunits uniquely expressed by the pBAF complex, have been found to be mutated in approximately 1%–8% of human cancers." (PMID 41387924, 2025). "Loss of ARID2 has been associated with increased tumor growth, impaired DNA repair, and heightened metastatic potential, while ARID1A deficiency promotes cancer cell proliferation and invasion, including bone metastasis." (PMID 40872531, 2025). "Up to 25% of human cancers carry mutations in at least one of nine SWI/SNF subunit genes including SMARCA1 and 2, SMARCB1, ARID1A/B, PBRM1, and ARID2." (PMID 38085333, 2024). "USP2 and ARID2 demonstrated protein-protein interaction and overlapping localization in cancer cell models." (PMID 36567903, 2022). "Among the six SWI/SNF genes, ARID1A and SMARCB1 were, respectively, the most and least frequently mutated genes in the majority of the cancer types (ARID1A, 10.7%; SMARCA4, 6.0%; ARID1B, 4.7%; ARID2, 4.0%; PBRM1, 3.5%; SMARCB1, 1.3%)." (PMID 36371186, 2022). "Study results showed that cancer cells transfected with USP2 shRNAs exhibited significantly promoted ARID2 protein degradation compared with a control group." (PMID 36567903, 2022). "To summarize, we confirmed that USP2 suppressed cancer cell migration and invasion capabilities through ARID2." (PMID 36567903, 2022). "We evaluated the clinicopathological correlates of the 7 SMGs, together with 6 additional cancer genes identified from at least 2 previous HCC genomics studies and mutated in ≥3 HCCs of the current cohort (APOB, ARID2, CDKN2A, KEAP1, RB1 and TSC2)." (PMID 35508466, 2022). "Other mutated cancer genes included those involved in Wnt signaling (APC, AMER1), mitogen signaling (KRAS, BRAF), epigenetic modification (ARID1A, ARID2, DNMT3A, NCOA3) and DNA repair (RAD50, BRIP1, ERCC5, RECQL4)." (PMID 33776923, 2021). "SWI/SNF subunits are the most commonly mutated chromatin-regulatory complexes in human cancer, mutated in 19.6% cancers, with subunits ARID1A, PBRM1, SMARCA4, and ARID2 already part of routine cancer diagnostics." (PMID 34944438, 2021). "Through integrative analyses of the consistently up-regulated genes, ARID2 ChIP-seq data and survival-related genes from the cancer genome atlas (TCGA)-LUAD dataset, we found three candidate genes including Hspa1a, Pkm and Tsku." (PMID 34858604, 2021). "To evaluate the prevalence of PBAF complex mutations, we queried the pan-cancer TCGA atlas (n = 10,359) and analyzed all three genes in the complex (PBRM1, ARID2, and BRD7)." (PMID 32820162, 2020). "Here we review the current knowledge about the involvement of ARID2 in cancer in general and in HCC more specifically." (PMID 32977645, 2020). "ARID2 gene showed damaged score in eight patients, and also known as cancer-related gene, but hardly having a pathophysiological relationship to BRONJ." (PMID 31747953, 2019). "ARID2 knockout studies showed that ARID2 is required for proper nucleotide excision repair (NER) of DNA damage induced by UV and cancer-causing compounds in HCC." (PMID 31056726, 2019). "BAF200, also known as ARID2, encoded by the BAF200 gene, is a unique subunit of the PBAF chromatin remodeling complex, and inactivating mutations have been reported in a variety of human cancers." (PMID 29482581, 2018).